INS (insulin)
Diseases named in the same sentence as INS in open-access papers (continued):
Sharing a sentence is not in itself a finding about the gene and the disease.
Obesity (continued). "We then asked the question of how ACM glucose metabolism is altered in mice rendered insulin‐resistant by diet‐induced obesity (DIO)." (PMID 41184177, 2025). "These SCFAs also modulate metabolic parameters by influencing glucose and lipid metabolism through G-protein-coupled receptor activation and histone deacetylase inhibition, thereby inducing anti-obesity and insulin-sensitizing effects." (PMID 40870819, 2025). "The “carbohydrate-insulin model” has been proposed to explain how excessive carbohydrate consumption can lead to obesity and its downstream cardiometabolic complications." (PMID 40667440, 2025). "Hyperprolactinaemia promotes weight gain, obesity and the development of metabolic syndrome by inhibiting physiological dopaminergic tone and disrupting glucose–insulin and lipid metabolism." (PMID 40464046, 2025). "In male offspring, associated dmCpGs were linked to known obesity-related genes including B4GALNT4 (cg25020933, cg15762098), ADCY9 (insulin secretion and thyroid hormone synthesis) (cg00610508), ADRB1 (cg13848598) and ATP10D (cg14009629)." (PMID 40410506, 2025). "The knockout of Cidea and Cidec respectively in mice has been shown to result in a lean phenotype and resistance to high-fat diet (HFD)-induced obesity, accompanied by increased insulin sensitivity." (PMID 40305497, 2025). "Butyrate, as a key metabolite, improves insulin sensitivity and supports adipose tissue metabolism, making it a potential therapeutic target in obesity management." (PMID 40864791, 2025). "Hypothalamic inflammation, particularly in the arcuate nucleus, emerges early in diet-induced obesity and contributes to leptin and insulin resistance, disrupting the central regulation of food intake and energy expenditure." (PMID 40564149, 2025). "In murine models, treatment with MOTS-c improves insulin responsiveness, counteracts obesity induced by high-fat feeding, and reduces β-cell damage driven by autoimmune mechanisms via regulation of mTORC1 activity." (PMID 41465308, 2025). "Apelin secretion is insulin-dependent, therefore its levels tend to soar in obesity and hyperinsulinemia." (PMID 41375608, 2025). "Cinnamon EO is rich in cinnamaldehyde, which stimulates the release of insulin from the pancreas and inhibits adipocyte differentiation and adipogenesis, thus exerting an anti-obesity effect." (PMID 41199858, 2025). "In mice, these obesity‐induced epigenetic modifications (such as persistent histone methylation at inflammatory gene loci) led to accelerated weight regain and blunted insulin sensitivity upon return to a high‐fat diet." (PMID 40684278, 2025). "Obesity, which is widespread in T2DM, is strongly associated with higher BMD, probably through mechanical loading and hormonal factors, including insulin, estrogen, and leptin." (PMID 40896277, 2025). "SGLT2is were initiated more frequently in patients with higher CV comorbidities and proteinuria, while GLP1RAs were initiated more frequently in patients with obesity, compared to insulin initiators." (PMID 39860655, 2025). "For example, wheat bran-derived ARs have been found to improve glucose tolerance and insulin sensitivity by suppressing hepatic lipid accumulation and intestinal cholesterol absorption in mice, preventing the development of diet-induced obesity." (PMID 39857767, 2025). "We demonstrated that miR-30a increased the abundance of smaller adipocytes in subcutaneous WAT after HFD feeding, which predicts insulin sensitivity in obesity." (PMID 40471675, 2025). "Children and adolescents with obesity and adequate insulin sensitivity have distinct variations in glucagon and incretin production, indicating opportunities for tailored therapies." (PMID 40649920, 2025). "Insulin is a crucial regulator of synovial inflammation and catabolism, and individuals with IR frequently exhibit MetS, such as obesity." (PMID 39794440, 2025).
Obesity (continued). "This begins with inadequate insulin production or dysfunctional insulin, which is usually due to one of the many factors including obesity, sedentary lifestyle, or oxidative stress." (PMID 40860627, 2025). "Distinct gene sets correlated with important clinical variables of obesity, fat distribution measures, as well as insulin, glucose, and lipid metabolism." (PMID 40118008, 2025). "The metabolic improvement observed with treatment is likely attributable to its anti-obesity effects and consequent improvement in adipose tissue insulin sensitivity." (PMID 41199017, 2025). "Obesity, satiety, glucocorticoids, insulin, and acute infection increase leptin levels, whereas cold stimulation, fasting, and testosterone decrease leptin levels." (PMID 39812542, 2025). "Unlike white adipose tissue, which primarily stores excess energy, BAT has the unique ability to generate heat through thermogenesis, increasing the basal metabolic rate and enhancing insulin sensitivity, potentially mitigating obesity-related health risks." (PMID 40004080, 2025). "Studies have shown that obesity-related factors—including low-grade chronic inflammation, altered cytokine levels, insulin resistance, and oxidative stress—affect the progression of TC." (PMID 40530706, 2025). "In conclusion, gut dysbiosis contributes to obesity through a complex network of endocrine disruptions, involving insulin, leptin, ghrelin, GLP-1, PYY, cortisol, serotonin, and sex hormones." (PMID 41010468, 2025). "Obesity promotes several metabolic disturbances—such as insulin resistance, dysregulated adipokine production, chronic inflammation, and myocardial lipotoxicity—all of which contribute to cardiac dysfunction." (PMID 41282294, 2025). "For example, when rodents were given intracerebroventricular injections of FGF21, their hepatic insulin sensitivity and metabolic rate increased in cases of diet-induced obesity." (PMID 39744501, 2025). "VCO increases the absorption of calcium and magnesium, compared to other types of oils with a high content of long-chain fatty acids; it prevents obesity, and, hence, decreases the incidence of or prevents diabetes, and induces insulin sensitivity." (PMID 40863333, 2025). "LVDD appears to be related to obesity level and fasting insulin levels and reduced exercise capacity, however, obesity duration was not considered." (PMID 40297180, 2025). "Inflammation in individuals with obesity is one of the major factors disrupting normal insulin signaling." (PMID 40944223, 2025). "Previous studies have tested multiple therapeutic combinations with FGF21 or FGF21 alone and have found that FGF21 alone is sufficient to improve insulin sensitivity and reduce obesity in HFD-fed mice." (PMID 40663389, 2025). "Obesity occurs through the expansion of adipose tissue in an unhealthy and dysfunctional manner, where patients develop inflammation and insulin resistance." (PMID 41207623, 2025). "GDF15 improves metabolic parameters, including insulin sensitivity and glycemic control, in obesity models via glial cell line-derived neurotrophic factor (GDNF) family receptor α–like (GFRAL) receptor signaling." (PMID 40301996, 2025). "In obesity, low-grade systemic inflammation is established together with dysregulated insulin signaling." (PMID 40076851, 2025). "Obesity often leads to a chronic low-grade inflammatory state, with excess adipose tissue producing pro-inflammatory cytokines that impair insulin signaling and contribute to metabolic dysfunction." (PMID 40641901, 2025). "EcNA intervention induces an anti-obesity effect on eVAT, possibly by stimulating energy production, and expenditure and by improving insulin sensitivity in MASLD mouse model." (PMID 40211057, 2025). "In obesity, the ability of peripheral tissues (e.g., skeletal muscle, liver, adipose) to respond to insulin is impaired, increasing the insulin demand on β-cells." (PMID 41282294, 2025).
Obesity (continued). "Epididymal adipose tissue is a major fat depot critically involved in lipid storage, systemic insulin sensitivity, and inflammation, and is significantly affected by obesity induced by a high fat diet." (PMID 40557240, 2025). "This imbalance reduces satiety, increases the glycemic response, and disrupts insulin signaling, ultimately leading to persistent cravings, increased energy intake, and a self-reinforcing cycle of weight gain and obesity." (PMID 40014232, 2025). "In vivo studies have reported that NOD2 stimulation by MDP improves insulin sensitivity, enhances glucose tolerance, and prevents obesity." (PMID 41340462, 2025). "Selectively targeting N/OFQ, encoded by the Pnoc gene, in B cells mitigates the adverse metabolic effects of diet-induced obesity and enhances insulin sensitivity and glucose tolerance." (PMID 40662198, 2025). "Influenced by factors such as diet and metabolism, abnormal methylation is associated with obesity and gestational diabetes mellitus (GDM), affecting genes involved in glucose and lipid metabolism, inflammation, and insulin signaling." (PMID 41302116, 2025). "Enhanced UCP1 abundance and an increase in the thermogenic capacity of the BAT have been shown to reduce obesity and improve glucose tolerance and insulin sensitivity in high-fat diet-fed mice." (PMID 40983918, 2025). "FDA‐approved GAA inhibitors, such as acarbose or miglitol, are effective at improving insulin action and glycemic control while also being effective at reducing fatty liver in individuals with obesity and type 2 diabetes." (PMID 40108792, 2025). "Known for its ability to improve gut barrier integrity and metabolic health, Akkermansia muciniphila has been shown to reduce body fat, enhance insulin sensitivity, and decrease inflammation, making it a promising candidate for obesity treatment." (PMID 40171165, 2025). "Clinical trials report improvements in insulin sensitivity, reductions in inflammatory markers, and body weight management in individuals with obesity." (PMID 40733199, 2025). "In adults with overweight/obesity, substantial evidence supports that exercise enhances glycemic control by boosting insulin sensitivity and glucose uptake in muscles." (PMID 40533648, 2025). "LXRs serve as key metabolic regulators in obesity by modulating lipogenesis, maintaining cholesterol homeostasis, enhancing insulin sensitivity, and inhibiting inflammation." (PMID 41438090, 2025). "Specifically, Yakut T2D patients showed significantly higher pPGS for the Beta Cell 1, Hyper Insulin, and Liver-Lipid clusters compared to other populations (P ≤ 0.05, Mann-Whitney), while the Obesity pPGS (P ≤ 0.05) was lower in the Yakut T2D group." (PMID 41001674, 2025). "In contrast, exercise decreases obesity-associated inflammation and reduces fibrosis in WAT and improves glucose and insulin homeostasis." (PMID 40522819, 2025). "This was followed by augmented insulin sensitivity, decreased obesity, and modifications in lipid and amino acid metabolism." (PMID 41030838, 2025). "A total of 10 papers evaluating the effect of the 5:2 diet on insulin intervention in overweight and obesity contained 568 subjects, with 280 in the 5:2 diet group and 288 in the control group." (PMID 40041761, 2025). "The mTORC1 signaling pathway, central to acne pathogenesis, is also activated in obesity and MetS, promoting lipid accumulation, insulin resistance, and inflammatory responses." (PMID 40358870, 2025). "Butyrate has been shown to ameliorate obesity in diet-induced obese mice, improve insulin sensitivity, and alleviate lipid disorders." (PMID 40282717, 2025). "In contrast, healthy and isolated criterion groups showed relatively stable or mildly increasing HOMA-IR and fasting insulin levels, with steeper increases in the presence of obesity." (PMID 40823908, 2025). "Collectively, these data indicate that TPMD exerts efficient insulin sensitization and metabolic improvements in both obesity models." (PMID 41473291, 2025).
Obesity (continued). "Inhibiting TBK1 with amlexanox improves obesity, insulin sensitivity, and glucose tolerance in HFD‐fed mice, ob/ob mice, and T2D patients." (PMID 39158380, 2025). "Women have a more pronounced antilipolytic effect of insulin than men, but this sex dimorphism is only observed when obesity is present." (PMID 41492388, 2025). "In the context of obesity, elevated glucose and fatty acids increase insulin demand and contribute to β-cell oxidative stress." (PMID 41372122, 2025). "In a study, Bacteroides acidifaciens were related to the prevention of obesity, through the improvement of insulin sensitivity and energy metabolism." (PMID 41048220, 2025). "Typically reduced in obesity, it exerts anti-inflammatory, anti-proliferative, and insulin-sensitizing effects on a variety of cell types." (PMID 40806335, 2025). "MicroRNAs (miRNAs) are critical mediators of gene expression, regulating various aspects of adipogenesis, insulin signaling, and inflammation during obesity." (PMID 41228448, 2025). "At baseline, compared with participants in the overweight/obesity trial, participants in the T2D trial had higher mean glucose, insulin, and HbA1c." (PMID 41451263, 2025). "Obesity disrupts insulin signaling and glucose metabolism by shifting the emphasis of the adipose secretome to a pro-inflammatory status." (PMID 40564914, 2025). "Nevertheless, prolonged SREBP-1c activation in obesity can result in excessive lipid synthesis, leading to the development of hypertrophic adipocytes and lipotoxicity, which ultimately impairs insulin sensitivity." (PMID 40002389, 2025). "Obesity also often leads to elevated levels of insulin and free IGF-1, which also enhances mitogenesis in cancer cells." (PMID 39924587, 2025). "We found a positive correlation between leisure TV watching and obesity‐related phenotypes (total cholesterol, triglyceride, BMI, visceral adipose tissue volume, T2D, and fasting insulin)." (PMID 40041789, 2025). "NE has been shown to modulate insulin signaling, with its deletion leading to improved insulin sensitivity in an obesity mouse model." (PMID 40370443, 2025). "Beige adipocytes enhance glucose and lipid uptake, reduce insulin demand, and increase energy expenditure, representing promising therapeutic targets for obesity and T2DM." (PMID 41002965, 2025). "10.3389/fendo.2023.1326546.This study provides robust evidence on how obesity disrupts the hypothalamic-pituitary-ovarian (HPO) axis through insulin resistance, chronic inflammation, and adipokine secretion." (PMID 40238039, 2025). "The position candidate gene INPPL1 has been discovered in Landrace pigs, which has a negative regulatory effect on diet induced obesity and participates in the regulation of insulin function." (PMID 40777826, 2025). "Insulin levels decreased significantly (p < 0.001) from 114.4 ± 63.5 pmol/L to 92.4 ± 53.1 pmol/L following treatment, suggesting that obesity‐related high insulin levels can be improved following walking therapy." (PMID 40464347, 2025). "The observed LEP upregulation in the OBS treatment group aligns with evidence suggesting that folic acid influences lipid metabolism, insulin sensitivity, and inflammatory pathways in obesity models." (PMID 40292473, 2025). "Promotes browning of white adipose tissue (WAT), activates brown adipose tissue (BAT), increases mitochondrial biogenesis, improves insulin sensitivity, enhances thermogenesis, and reduces obesity in mice." (PMID 39963239, 2025). "Current evidence suggests that EDs contribute to the development of obesity and MetS by disrupting hormonal balance, altering adipogenesis, and impairing insulin signaling." (PMID 41488238, 2025). "Keywords with an occurrence frequency of ≥100, such as “inflammation,” “insulin-resistance,” and “obesity,” highlight popular themes within this research domain." (PMID 40453651, 2025).
Obesity (continued). "In general, PPAR-γ is a potent modulator of whole-body lipid metabolism and insulin sensitivity, making its upregulation a compensatory mechanism to manage excess lipid intake and storage in obesity." (PMID 39762333, 2025). "Air pollution exposure is strongly correlated with impaired insulin signaling, increased leptin resistance, and elevated inflammatory markers in the brain, mirroring physiological changes observed in obesity." (PMID 41515969, 2025). "Semaglutide, which is approved for managing T2D and obesity, works by enhancing insulin secretion, thereby reducing glucagon release, lowering blood glucose levels, and suppressing appetite, leading to weight loss." (PMID 40283457, 2025). "Treatment with CAR agonists alleviates hepatic steatosis in both HFD-fed and ob/ob mice, enhances insulin sensitivity, improves glucose and lipid metabolism, and prevents diet-induced obesity." (PMID 41438090, 2025). "Deletion of myostatin in mice also resulted in decreased fat mass, increased muscle mass, improved insulin sensitivity and resistance to diet‐induced obesity." (PMID 39764565, 2025). "Studies reveal that obesity-driven matrix deposition creates fibrotic microenvironments that sustain inflammatory responses and compromise insulin signaling pathways." (PMID 40630101, 2025). "Studies indicate that BAIBA can improve diabetic cardiomyopathy, obesity-induced atrial fibrillation, and atrial remodeling by inhibiting oxidative stress, reducing inflammation, and increasing insulin sensitivity." (PMID 40036545, 2025). "The journal retracts the article titled “Lemon Balm Extract ALS-L1023 Regulates Obesity and Improves Insulin Sensitivity via Activation of Hepatic PPARα in High-Fat Diet-Fed Obese C57BL/6J Mice”, cited above." (PMID 39959987, 2025). "Several studies have noted the frequent coexistence of overweight or obesity—acknowledged as important contributors to hyperglycemia—together with relatively low serum insulin levels and other metabolic abnormalities." (PMID 41153735, 2025). "The pro-inflammatory state, characteristic of obesity, is known to induce insulin resistance in skeletal muscles and the liver, subsequently disrupting their normal metabolic functions." (PMID 40391013, 2025). "Obesity also amplifies the pro-inflammatory environment of pregnancy, compounding the stress on insulin signaling pathways." (PMID 40076938, 2025). "WAT becomes dysfunctional in obesity, creating a pro-inflammatory, hyperlipidemic, and insulin-resistant environment that ultimately contributes to the development of metabolic and vascular complications." (PMID 39857433, 2025). "These compounds exhibit potent antioxidant, anti-inflammatory, hypolipidemic, anti-obesity, and insulin-sensitizing effects." (PMID 41141263, 2025). "As such, consistently high insulin concentrations have been shown to increase adiposity and, over time, contribute to obesity." (PMID 40931394, 2025). "While this function is beneficial under normal physiological conditions, in obesity, chronic mTORC1 activation leads to insulin desensitization, which paradoxically reduces glucose clearance from the bloodstream." (PMID 40218884, 2025). "Similar to DEGs, many DMGs were enriched in insulin secretion, T2DM, circadian rhythm, and cholesterol metabolism pathways associated with obesity and metabolism." (PMID 41220714, 2025). "In white adipose tissue (WAT), obesity induces a shift from anti-inflammatory to pro-inflammatory macrophage phenotypes, contributing to insulin resistance and tissue fibrosis." (PMID 41396217, 2025). "These insights highlight the intertwined roles of dopamine and insulin in energy balance and suggest new therapeutic avenues aimed at restoring dopamine–insulin homeostasis to prevent or reverse obesity in subjects with low D2 receptor density." (PMID 41279682, 2025).